TBC1D4 (TBC1 domain family member 4)
Description:
May act as a GTPase-activating protein for RAB2A, RAB8A, RAB10 and RAB14. Isoform 2 promotes insulin-induced glucose transporter SLC2A4/GLUT4 translocation at the plasma membrane, thus increasing glucose uptake.
Synonyms: AS160; KIAA0603; DKFZp779C0666; NIDDM5
Tractability: PROTAC: ubiquitination databases record sites on it; its protein half-life has been measured.
Gene: Protein-coding gene on chromosome 13 (75,283,503 to 75,482,651, reverse strand). Ensembl gene ENSG00000136111.
Subcellular location: Cytoplasm
Subcellular location (Human Protein Atlas): Cytosol
Pathways (Reactome):
Vesicle-mediated transport: Translocation of SLC2A4 (GLUT4) to the plasma membrane
Gene Ontology:
Molecular function: protein binding; GTPase activator activity
Biological process: cellular response to insulin stimulus; vesicle-mediated transport
Cellular component: cytosol; Golgi apparatus; cytoplasm
Genetic constraint (gnomAD): Loss-of-function variants: 113 observed, 135.78 expected, observed/expected ratio (o/e) 0.83, 90% interval 0.71 to 0.97. The upper end of that interval is the gene's LOEUF score, 0.97, which puts it in group 4 of 6, group 1 being the genes least tolerant of losing a copy. Missense variants: 1,422 observed, 1,620.6 expected, observed/expected ratio (o/e) 0.88, 90% interval 0.84 to 0.92. Synonymous variants: 606 observed, 640.61 expected, observed/expected ratio (o/e) 0.95, 90% interval 0.88 to 1.01.
Homologues: Orthologues: chimpanzee TBC1D4 (99% identical), macaque TBC1D4 (98% identical), dog TBC1D4 (92% identical), pig TBC1D4 (91% identical), rabbit TBC1D4 (91% identical), mouse Tbc1d4 (90% identical), rat Tbc1d4 (90% identical), guinea pig TBC1D4 (90% identical), tropical clawed frog tbc1d4 (69% identical), zebrafish tbc1d4 (61% identical). Paralogues in human: TBC1D1 (47% identical), RABGAP1 (13% identical), RABGAP1L (12% identical), TBC1D2 (12% identical), TBC1D9B (12% identical), TBC1D9 (11% identical), EVI5L (10% identical), TBC1D10B (10% identical), EVI5 (10% identical), TBC1D2B (10% identical), TBCK (10% identical), TBC1D8 (10% identical), and 33 more.
Diseases named in the same sentence as TBC1D4 in open-access papers:
TBC1D4 is named in the same sentence as 51 diseases in open-access papers, as found by Europe PMC text mining. Sharing a sentence is not in itself a finding about the gene and the disease. The quoted sentences say what the papers report.
Insulin resistance (42 papers, 2011 to 2026). Increased resistance towards insulin, that is, diminished effectiveness of insulin in reducing blood glucose levels. "While the canonical insulin pathway (PI3K/Akt/TBC1D4) is the most potent and specific mechanism in the postprandial state, its dysfunction is centrally associated with insulin resistance and type 2 diabetes mellitus (T2DM)." (PMID 42074118, 2026). "Other potentially damaging variants of TBC1D4 were previously reported to cause a higher risk of type 2 diabetes and insulin resistance." (PMID 38932873, 2024). "Genetic variants in TBC1D4 are associated with insulin resistance and type-2 diabetes in the Greenlandic Inuit population, and regulation of TBC1D4 is impaired in skeletal muscle of people with type 2 diabetes." (PMID 39026321, 2024). "In homozygous carriers of a TBC1D4 variant, conferring postprandial insulin resistance, the risk of T2D is markedly higher." (PMID 37129117, 2023). "A common muscle-specific TBC1D4 p.Arg684Ter loss-of-function variant has been identified previously in arctic populations as a major contributor to the development of insulin resistance and T2DM." (PMID 36707786, 2023). "A truncated form of TBC1D4 confers insulin resistance and increases diabetes and cardiovascular risk in the Inuit population in Greenland." (PMID 36246906, 2022). "A recent study identified a common mutation in TBC1D4 causing muscle-tissue-specific insulin resistance and postprandial hyperglycaemia." (PMID 27562574, 2016). "Moreover, in isolated populations, even higher prevalence rates of loss-of-function mutations in AKT2 and TBC1D4, both involved in insulin signalling and implicated in monogenic insulin resistance, have been described." (PMID 35618782, 2022). "Rare heterozygous mutations in TBC1D4, which regulates insulin-responsive glucose transport, also may cause severe insulin resistance." (PMID 35618782, 2022). "Thus, the mechanisms by which cancer causes insulin resistance in vivo seem to be different from those causing insulin resistance in obesity and T2D, where muscle Akt and TBC1D4 signaling is either unaffected or reduced." (PMID 33801684, 2021). "In line with this, acute exercise has been reported to alleviate lipid-induced insulin resistance in human skeletal muscle by increasing interaction at the level of TBC1D4." (PMID 37153211, 2023). "Protein‐coding SNVs in TBC1D4 and TBC1D1 have been associated with insulin resistance, obesity, and type II diabetes." (PMID 35579274, 2022). "Similarly, familial studies of patients with acanthosis nigricans and hyperinsulinemia revealed a loss-of-function mutation in TBC1D4, which encodes for a protein involved in GLUT4 trafficking; loss of its function causes severe insulin resistance." (PMID 40013621, 2025). "Thus, the role of TBC1D4 deficiency in T2DM, and the contribution of systemic insulin resistance to the cardiac phenotype remains to be further investigated." (PMID 36707786, 2023). "Reduced Akt and TBC1D4 phosphorylation has been observed in some models of insulin resistance." (PMID 29599292, 2018). "Insulin resistance triggered by pharmacological or genetic inhibition of CoQ biosynthesis occurred independently of consistent defects in insulin signalling to the key regulators of glucose transport (Akt or the Akt substrate TBC1D4), or changes in GLUT4 expression." (PMID 29402381, 2018). "From a practical standpoint, studies of insulin resistance would be well served by immunoblotting for TUG cleavage products, possibly in addition to phosphorylated Akt or Tbc1D4 proteins." (PMID 36246906, 2022). "However, our studies with MitoPQ, where we observed insulin resistance without defects in Akt/TBC1D4, raise questions over whether such changes in insulin signaling are the primary driver of insulin resistance." (PMID 29599292, 2018).
type 2 diabetes (26 papers, 2011 to 2026). "In fact, TBC1D4 (p.Arg684Ter) appears to be the major genetic cause for type 2 diabetes in both the Greenlandic and Canadian Inuit." (PMID 32591906, 2020). "It is also possible that the causal variant behind the observed type 2 diabetes association is Inuit-specific, similar to the risk variant in TBC1D4." (PMID 29926116, 2018). "In a recent study using a standard additive genetic model, we identified a TBC1D4 loss-of-function variant with a large recessive impact on risk of type 2 diabetes in Greenlanders." (PMID 29926116, 2018). "We found indication of an interaction effect, suggesting an attenuation in the association between the TBC1D4 p.Arg684Ter risk variant and odds of type 2 diabetes per kJ kg−1 day−1 unit increase in daily physical activity (OR 0.99 [95% CI 0.97, 1.00], p = 0.11)]." (PMID 33912980, 2021). "Based on the variant’s high frequency and the clinical characterisation of homozygous TBC1D4 risk variant carriers, it has been suggested that diagnostic strategies for type 2 diabetes should include 2 h OGTT and/or TBC1D4 genotype risk stratification in Arctic populations." (PMID 33912980, 2021). "Besides the established TBC1D4 locus, we identified a novel genome-wide significant variant for risk of type 2 diabetes in ITGA1, and a variant near LARGE1 showing a suggestive association." (PMID 29926116, 2018). "More research is needed to identify the causal variants, to elucidate the biological mechanisms underlying the association with type 2 diabetes, and to clarify whether these novel variants distinguish type 2 diabetes subtypes with specific aetiology, as demonstrated for TBC1D4." (PMID 29926116, 2018). "Moreover, a recent genome-wide association study among Inuit in Greenland has discovered a frequent variant of the gene TBC1D4 associated with type 2 diabetes, which has been estimated to account for more than 10 percent of all type 2 diabetes cases in Greenland." (PMID 27073876, 2016). "A similar mechanism has been evoked to explain the increase in type II diabetes in Greenlandic populations, in response to an increase in carbohydrate intake with diet and the presence of a single TBC1D4 SNP (rs61736969)." (PMID 39684907, 2024). "Type 2 diabetes was shown to decrease expression of Tbc1d4 in skeletal muscle of streptozocin-treated rats and diabetic Goto-Kakizaki rats (in comparison to control Wistar rats)." (PMID 33769190, 2021). "While our primary aim was to investigate the effect of the TBC1D4–physical activity interaction on 2 h plasma glucose, our second aim was to investigate the effect of the interaction on the probability of having type 2 diabetes." (PMID 33912980, 2021). "Regular exercise training has been shown to regulate the phosphorylation of TBC1 domain family member 4 (TBC1D4) in skeletal muscle from individuals with type 2 diabetes, indicating a role for RabGAP in the insulin-sensitising effects of exercise training." (PMID 33912980, 2021). "For instance, given reports that statins increase diabetes risk, it is interesting that we identify a deQTL for TBC1 domain family member 4 (TBC1D4), a gene which plays a role in glucose homeostasis and type 2 diabetes." (PMID 32787775, 2020). "In this study, we observed three loci, TBC1D4, ITGA1 and LARGE1, harbouring variants with large recessive effects on the risk of type 2 diabetes in Greenlanders, the latter, however, having weaker statistical support." (PMID 29926116, 2018). "Impaired insulin-induced GLUT4 traffic and phosphorylation of TBC1D4 are restored by endurance exercise-training in skeletal muscle of type 2 diabetes patients." (PMID 22253718, 2012). "A study with Inuit in Canada with the same allele frequency and postprandial effect of TBC1D4, found that in carriers with prediabetes or type 2 diabetes, 32% would have remained undiagnosed without an OGTT29." (PMID 33328529, 2020).
type 2 diabetes (continued). "While genetic variants such as TBC1D4 and TCF7L2 result in up to 50% increased risk of type 2 diabetes by diminishing the incretin effect and impairing glucagon-like peptide 1–induced insulin secretion, a fiber-rich diet may stimulate glucagon-like peptide 1 and mitigate this genetic risk." (PMID 38049803, 2023). "We included 240 individuals with type 2 diabetes (of these, 38 individuals were homozygous TBC1D4 p.Arg684Ter variant carriers) and 1969 individuals with normal glucose tolerance as a control group (of these, 28 individuals were homozygous TBC1D4 p.Arg684Ter variant carriers) in a logistic model." (PMID 33912980, 2021). "For example, the TBC1D4 nonsense variant p.Arg684ter was initially found in Inuits from Greenland, where it has a high prevalence (17%) and large effect size (homozygous carriers have an approximately tenfold increased risk of type 2 diabetes), but is very rare or absent elsewhere." (PMID 34595549, 2021). "Notably, however, this TBC1D4 loss-of-function variant was discovered via analyses of a type 2 diabetes-related trait, 2 h plasma glucose, on which it had an extremely large effect, and not via analyses of type 2 diabetes." (PMID 29926116, 2018). "For example, studies have shown that TBC1D1 and TBC1D4 participate in intracellular GLUT4 vesicle transport and regulate blood glucose and that the site-specific phosphorylation of TBC1D4 is closely related to type 2 diabetes recovery." (PMID 25984991, 2015).
diabetes (12 papers, 2019 to 2026). "In this study we tested if diabetes and the TBC1D4 variant were associated with CVD risk in Inuit in Greenland." (PMID 33328529, 2020). "We do not know if CVD risk for Inuit with diabetes is the same as for Caucasians with diabetes or if the TBC1D4 variant confers increased risk of CVD." (PMID 33328529, 2020). "The pathophysiology connecting the TBC1D4 variant to diabetes involves the defective protein it produces." (PMID 33328529, 2020). "A common ground between the TBC1D4 variant, diabetes and cardiovascular outcomes, is found in the “common soil hypothesis”, a shared pathophysiological pathway of diabetes and CVD through obesity, insulin resistance, dyslipidemia and inflammation." (PMID 33328529, 2020). "HO carriers of the TBC1D4 variant were in higher number in the diabetes group compared to the normoglycemia group, n = 47 (13.7%) and n = 71 (2.3%) and conversely TBC1D4 WT genotype was lower in the diabetes group than the normoglycemia group n = 205 (59.8%) and n = 2205 (70.3%) respectively." (PMID 33328529, 2020). "Tbc1d4, Acadl, Acsl1 and Fabp4 were found to be associated with early diabetes in GK rats for the first time, which may provide a new scope for pathogenesis of postprandial hyperglycemia." (PMID 31141985, 2019). "However, this is only a hypothesis and we cannot confirm that the variant in TBC1D4 was directly causative and correlated with diabetes in our patient." (PMID 38932873, 2024). "An explanation could be, that there could be undiscovered CVD protective variants or Inuit specific interactions with diet or metabolic traits affecting CVD risk, or the TBC1D4 variant could induce less dangerous diabetes form like GCK-MODY (Glycokinase Maturity Onset Diabetes of the Young)." (PMID 33328529, 2020). "This is the first study that suggests Tbc1d4, Acadl, Acsl1 and Fabp4 are associated with early diabetes in GK rats, which may provide a new scope for pathogenesis of postprandial hyperglycemia and controlling postprandial glucose levels in T2D patients at early stages." (PMID 31141985, 2019). "Diabetes was shown to down-regulate the expression of TBC1D4 in skeletal muscle and adipose tissue of humans and rodents." (PMID 33769190, 2021). "Furthermore, genetic mutations that occur in AS exons may lead to tissue-specific loss of function, as exemplified by a common muscle-specific TBC1D4 p.Arg684T variant, which accounts for more than 10% of all diabetes cases in Greenlandic and other Arctic populations." (PMID 33880624, 2021). "The aim was to examine the association between diabetes and incident CVD among Inuit in Greenland and determine if the common diabetogenic TBC1D4 variant confers increased risk of CVD." (PMID 33328529, 2020). "In light of increasing diabetes prevalence in the Inuit, it has been suggested that stratifying diabetes diagnoses based on an individual’s TBC1D4 p.Arg684ter genotype, and performing OGTTs in carriers of this variant, may be appropriate in this population." (PMID 34595549, 2021). "Neither diabetes nor the TBC1D4 variant significantly increased CVD risk among Inuit in Greenland in adjusted models." (PMID 33328529, 2020). "In conclusion, this study showed that neither diabetes nor the TBC1D4 variant significantly increased CVD risk in Inuit in Greenland." (PMID 33328529, 2020). "If replicated, this could suggest that diabetes associated with homozygosity for TBC1D4 p.Arg684ter is similar to MODY due to GCK mutations, and would impact on how diabetes is managed in individuals homozygous for TBC1D4 p.Arg684ter." (PMID 34595549, 2021). "Similarly, the TBC1D4 variant convincingly increases diabetes risk in Inuit populations, but it does not seem to convincingly increase CVD risk." (PMID 33328529, 2020). "This is the first study to analyse the sequence of the MTOR, TBC1D4, CACNA1E, SLC19A2 and KCNH6 genes in Polish patients with suspected MODY-X diabetes using the NGS method." (PMID 38932873, 2024).
diabetes (continued). "The present study showed that diabetes and exercise in warm water (35 °C) increased TBC1D1 and TBC1D4 compared to the healthy group." (PMID 38195613, 2024). "In adipose tissue of females presenting diabetes and obesity the decrease in TBC1D4 expression in comparison to non-diabetic and non-obese subject was noted." (PMID 33769190, 2021). "Here, it was shown that unless postprandial glucose levels were tested, 32% of TBC1D4 p.Arg684ter carriers with prediabetes (defined as fasting plasma glucose 5.6–6.9 mmol/l, 2 h 75 g OGTT plasma glucose 7.8–11.0 mmol/l and/or HbA1c 5.7–6.4% [39–46 mmol/mol]) and diabetes would remain undiagnosed." (PMID 34595549, 2021).
Hyperglycemia (8 papers, 2016 to 2026). An increased concentration of glucose in the blood. "The combination of lowered GLUT4 content and compromised insulin-stimulated GLUT4 translocation is suggested to lead to the postprandial hyperglycaemia and hyperinsulinaemia observed in the human homozygous TBC1D4 p.Arg684Ter variant carriers." (PMID 33912980, 2021).
Obesity (8 papers, 2014 to 2024). Accumulation of substantial excess body fat. "For example, in a patient diagnosed with obesity, a likely pathogenic frameshift in TBC1D4 was detected by targeted gene panel sequencing, yet WES failed to obtain this important genetic diagnosis." (PMID 37327085, 2023). "Insulin-stimulated TBC1D4 (Thr642) phosphorylation exhibited a trend to be repressed with obesity (P = 0.10); this difference became more evident after resveratrol treatment in pThr642 and pSer704 (P < 0.05)." (PMID 38324260, 2024). "Plx is the Drosophila ortholog of the related human Rab GAPs TBC1D1 and TBC1D4/AS160 that regulate the insulin-controlled traffic of the glucose transporter GLUT4 and have been linked to obesity." (PMID 25453831, 2014). "In the present study, resveratrol improved insulin-mediated signal transduction [insulin-stimulated phosphorylation of IRS1 (Tyr632), Akt (Ser473), and TBC1D4 (Thr642)] in the myotubes from lean individuals, but not in the myotubes from individuals with severe obesity." (PMID 38324260, 2024). "Resveratrol further increased IRS1, Akt, and TBC1D4 insulin-stimulated phosphorylation and SIRT1 content in myotubes from lean women, but not in women with severe obesity." (PMID 38324260, 2024).
Glucose intolerance (3 papers, 2019 to 2023). Glucose intolerance (GI) can be defined as dysglycemia that comprises both prediabetes and diabetes. "A common nonsense mutation in TBC1D4 (Arg684Ter) was recently identified in Greenlandic Inuit and other arctic populations and has been associated with severe glucose intolerance, reduced GLUT4 abundance in skeletal muscle and increased risk for T2DM." (PMID 36707786, 2023).
non-small cell lung carcinoma (3 papers, 2015 to 2019). A group of at least three distinct histological types of lung cancer, including non-small cell squamous cell carcinoma, adenocarcinoma, and large cell carcinoma. "Phosphorylation of at least two of the three further known Akt target proteins Proline-rich AKT1 substrate 1 (PRAS40), tuberous sclerosis 2 (TSC2) and TBC1 Domain Family Member 4 (TBC1D4) in non-small cell lung cancer cell lines also required Akt1-phosphorylation at T308 for their activation." (PMID 29562639, 2018). "In a study of non-small cell lung cancer, it was found that p-Akt(Thr308), but not p-Akt(Ser43) correlated with phosphorylation of three downstream substrates (PRAS40, TSC2, and TBC1D4), leading the authors to suggest that p-Akt(Thr308) represents a better measure of Akt activity in these tumors." (PMID 26793165, 2015).
diabetic nephropathy (2 papers, 2022 to 2025). "TBC1D4 is involved in glucose homeostasis and has been shown to control glucose transporter type 4 (GLUT4) in adipose and skeletal muscle cells, and is known to be associated with diabetic nephropathy." (PMID 39968160, 2025).
infarction (2 papers, 2020 to 2023). A localised pathological necrosis of tissue resulting from obstruction of the blood supply usually by a thrombus, an embolus, or vascular torsion. "I/R-induced myocardial injury was more pronounced in D4KO mice compared to WT littermates with knockout mice showing progressive impairment in cardiac function and a ~ 30% higher infarction size 3 weeks post surgery, indicating that TBC1D4 is required for the post infarction healing processes." (PMID 36707786, 2023).